CSGALNACT2 (chondroitin sulfate N-acetylgalactosaminyltransferase 2)
Description:
Transfers 1,4-N-acetylgalactosamine (GalNAc) from UDP-GalNAc to the non-reducing end of glucuronic acid (GlcUA). Required for addition of the first GalNAc to the core tetrasaccharide linker and for elongation of chondroitin chains.
Synonyms: GalNAcT-2; CHGN2; GALNACT2; PRO0082; MGC40204; ChGn-2; beta4GalNAcT
Tractability: Antibody: UniProt predicts a signal peptide or a membrane-spanning region. PROTAC: ubiquitination databases record sites on it; its protein half-life has been measured.
Gene: Protein-coding gene on chromosome 10 (43,137,831 to 43,185,302, forward strand). Ensembl gene ENSG00000169826.
Subcellular location: Golgi apparatus, Golgi stack membrane
Subcellular location (Human Protein Atlas): Endoplasmic reticulum
Pathways (Reactome):
Metabolism: CS-GAG biosynthesis
Gene Ontology:
Molecular function: acetylgalactosaminyltransferase activity; protein binding; glucuronosyl-N-acetylgalactosaminyl-proteoglycan 4-beta-N-acetylgalactosaminyltransferase activity; glucuronylgalactosylproteoglycan 4-beta-N-acetylgalactosaminyltransferase activity
Biological process: chondroitin sulfate proteoglycan biosynthetic process; dermatan sulfate proteoglycan biosynthetic process; proteoglycan biosynthetic process
Cellular component: membrane; Golgi membrane; Golgi apparatus; Golgi cisterna membrane
Genetic constraint (gnomAD): Loss-of-function variants: 26 observed, 40.7 expected, observed/expected ratio (o/e) 0.64, 90% interval 0.47 to 0.89. The upper end of that interval is the gene's LOEUF score, 0.89, which puts it in group 3 of 6, group 1 being the genes least tolerant of losing a copy. Missense variants: 392 observed, 511.41 expected, observed/expected ratio (o/e) 0.77, 90% interval 0.7 to 0.83. Synonymous variants: 147 observed, 179.51 expected, observed/expected ratio (o/e) 0.82, 90% interval 0.71 to 0.94.
Homologues: Orthologues: chimpanzee CSGALNACT2 (100% identical), macaque CSGALNACT2 (99% identical), pig CSGALNACT2 (98% identical), dog CSGALNACT2 (96% identical), rabbit CSGALNACT2 (95% identical), rat Csgalnact2 (94% identical), mouse Csgalnact2 (93% identical), guinea pig CSGALNACT2 (92% identical), tropical clawed frog csgalnact2 (76% identical), zebrafish csgalnact2 (72% identical), Drosophila melanogaster Csgalnact (38% identical). Paralogues in human: CSGALNACT1 (60% identical), CHSY1 (29% identical), CHSY3 (29% identical), B4GALNT4 (20% identical), B4GALNT3 (19% identical), CHPF2 (18% identical), CHPF (18% identical).
Diseases named in the same sentence as CSGALNACT2 in open-access papers:
CSGALNACT2 is named in the same sentence as 21 diseases in open-access papers, as found by Europe PMC text mining. Sharing a sentence is not in itself a finding about the gene and the disease. The quoted sentences say what the papers report.
colorectal cancer (4 papers, 2019 to 2024). A primary or metastatic malignant neoplasm that affects the colon or rectum. "Previous studies have revealed that CSGALNACT2 is associated with osteoarthritic of the knee, atherosclerosis, pediatric high-grade glioma, multiple myeloma, as well as colorectal cancer." (PMID 38082211, 2024). "In addition, abnormal expression of CSGALNACT2 is associated with osteoarthritic of the knee, atherosclerosis, pediatric high-grade glioma, multiple myeloma as well as colorectal cancer." (PMID 38082211, 2024). "Chondroitin sulfate N-acetylgalactosaminyltransferase 2 (CSGALNACT2), which plays a critical role in chain elongation during CS synthesis, is found to be downregulated in non-metastatic colorectal cancers, both right and left." (PMID 31013618, 2019).
atherosclerosis (1 paper, 2024). A disease characterized by the build-up of fatty material and calcium deposition in the arterial wall resulting in partial or complete occlusion of the arterial lumen. "KEGG pathway analysis demonstrated that the expression of CSGALNACT2 in ovarian cancer was correlated with the MAPK signaling pathway, Lipid and atherosclerosis, and Cell cycle, and the highest correlation was with the MAPK signaling pathway." (PMID 38082211, 2024).
colon adenocarcinoma (1 paper, 2024). "Meanwhile, the CSGALNACT2 expression was positively associated with the level of immune cells, and high expression of CSGALNACT2 was significantly associated with shorter overall survival (OS) rate in colon adenocarcinoma (COAD) and rectum adenocarcinoma (READ)." (PMID 38082211, 2024). "Previous studies have confirmed that the abnormal number of different immune cells could affect the tumor's immune response and CSGALNACT2 expression was positively associated with the level of immune cells in colon adenocarcinoma (COAD) and rectum adenocarcinoma (READ)." (PMID 38082211, 2024).
COVID-19 (1 paper, 2024). A disease caused by infection with severe acute respiratory syndrome coronavirus 2. "SRPK1, CSGALNACT2, B4GALT5, MEGF9, and KLF5 have increased mRNA expression in patients with severe COVID-19 compared with mild and non-COVID-19 patients." (PMID 38262689, 2024).
metastatic tumors (1 paper, 2013). "Although some variations were detectable only in non metastatic tumors, most were identified in both IDCs although several genes showed more intense changes in metastatic tumors than in non-metastatic, including PRCAN, CSGALNACT2, HS3ST4 and CHST12." (PMID 23327652, 2013).
ovarian carcinoma (1 paper, 2024). A malignant neoplasm originating from the surface ovarian epithelium. "At the same time, low expression of CSGALNACT2 is associated with the desert immune phenotype of ovarian cancer patients, making it more difficult to benefit from immunotherapy." (PMID 38082211, 2024). "To further explore the potential molecular mechanisms underlying the role of CSGALNACT2 in the development of ovarian cancer, we conducted RNA sequencing and analyzed mRNA differentially regulated mRNAs of HEY cells transfected with Vector and oeCSGALNACT2." (PMID 38082211, 2024). "Based on this phenomenon, we explored the possible role and mechanism of CSGALNACT2 in ovarian cancer." (PMID 38082211, 2024). "The observation of CSGALNACT2 downregulation in ovarian cancer tissue and metastatic lesions encourages us to further investigate the impact of experimental downregulation of CSGALNACT2 on HGSOC in vitro." (PMID 38082211, 2024). "The results of functional experiments showed that CSGALNACT2 can inhibit migration, invasion, and clone formation of ovarian cancer while promoting the motility of normal ovarian epithelium." (PMID 38082211, 2024). "And elevated CSGALNACT2 expression had longer survival outcomes in ovarian cancer patients with Paclitaxel or Docetaxel treatment by Kaplan–Meier survival analysis." (PMID 38082211, 2024). "To further investigate the effect of CSGALNACT2 expression on ovarian cancer prognosis under different immune cell-enriched or decreased conditions, we performed a survival analysis of ovarian cancer patients in the TCGA cohort." (PMID 38082211, 2024). "Then, in vivo and in vitro experiments were conducted to evaluate the role of CSGALNACT2 in the progression of ovarian cancer." (PMID 38082211, 2024). "In this study, we first discovered that CSGALNACT2 was significantly downregulated in ovarian cancer." (PMID 38082211, 2024). "CSGALNACT2 can significantly inhibit the migration, invasion, and clonogenic growth of ovarian cancer in vitro and is progressively lost during ovarian cancer progression in vivo." (PMID 38082211, 2024). "The Cancer Genome Atlas and GEPIA databases were used to assess the expression of CSGALNACT2 in ovarian cancer patients." (PMID 38082211, 2024). "Meanwhile, IHC analysis of in vivo experiments again showed that CSGALNACT2 expression gradually decreased with the progression of ovarian cancer, with the lowest expression in advanced stages and metastases." (PMID 38082211, 2024). "As an ovarian cancer suppressor gene, CSGALNACT2 inhibit ovarian cancer migration, and invasion by inhibiting the MAPK/ERK pathway." (PMID 38082211, 2024). "To determine the clinical significance of CSGALNACT2 in ovarian cancer, we assessed the expression of CSGALNACT2 in ovarian cancer patients by analyzing a public database." (PMID 38082211, 2024). "RNA-seq, qRT-PCR, and IHC were used to verify the expression of CSGALNACT2 in ovarian cancer tissues." (PMID 38082211, 2024). "Normal ovarian epithelial samples exhibited stronger staining of CSGALNACT2 than both ovarian cancer and ovarian cancer metastatic tissues." (PMID 38082211, 2024). "The results showed that the expression of CSGALNACT2 was lower in ovarian cancer compared with normal samples." (PMID 38082211, 2024). "The results showed that the downregulation of CSGALNACT2 significantly enhanced ovarian cancer cell migration and invasion abilities." (PMID 38082211, 2024). "CSGALNACT2 suppresses ovarian cancer migration and invasion via DUSP1 modulation of the MAPK/ERK pathway through RNA-seq, KEGG analysis, and Western blotting." (PMID 38082211, 2024). "First of all, we examined the expression of CSGALNACT2 in primary cells from both primary and metastatic ovarian lesions of the same ovarian cancer patient in our hospital." (PMID 38082211, 2024).
ovarian carcinoma (continued). "Subsequently, the role of CSGALNACT2 in the development of ovarian cancer was explored, and its effects and regulatory mechanisms were studied through in vivo and in vitro experiments." (PMID 38082211, 2024). "In summary, our research suggests that CSGALNACT2, as a new tumor suppressor gene in ovarian cancer, inhibit the development of ovarian cancer through the MAPK/ERK pathway." (PMID 38082211, 2024). "We demonstrated that the mRNA expression and protein level of CSGALNACT2 were significantly downregulated in ovarian cancer and ovarian cancer metastatic tissues." (PMID 38082211, 2024). "In addition, IHC staining analysis showed that CSGALNACT2 expression levels were lower in ovarian cancer tissues and metastatic tissues in the middle and late stages." (PMID 38082211, 2024). "Moreover, CSGALNACT2 expression was correlated with immune cell infiltration and had prognostic value in different immune cell-enriched or decreased ovarian cancer." (PMID 38082211, 2024). "Moreover, we detected the protein level of CSGALNACT2 using ovarian cancer tissues, which contained 28 normal and 36 tumor tissues, and 24 ovarian cancer tissues with metastasis." (PMID 38082211, 2024). "As an ovarian cancer suppressor gene, CSGALNACT2 inhibits the development of ovarian cancer, and it might be used as a prognostic biomarker in patients with ovarian cancer." (PMID 38082211, 2024). "However, unlike previous studies, this study found that CSGALNACT2 expression is downregulated in ovarian cancer and ovarian cancer metastasis, and high expression is associated with better prognosis in ovarian cancer patients." (PMID 38082211, 2024). "To explore the potential biological process and molecular function of CSGALNACT2 in ovarian cancer, we used GSEA to analyze the correlation of CSGALNACT2 expression with biological processes and molecular functions." (PMID 38082211, 2024). "While, when CD8+T cells decreased, the abnormal expression of CSGALNACT2 did not affect the prognosis of ovarian cancer." (PMID 38082211, 2024). "There are no studies that have evaluated the role of CSGALNACT2 in the regulation of ovarian cancer cells in ovarian cancer." (PMID 38082211, 2024). "Meanwhile, CSGALNACT2 is associated with different immune cell infiltration, and low expression of CSGALNACT2 in ovarian cancer patients is not conducive to immunosuppressive therapy." (PMID 38082211, 2024). "However, the mechanism of action of CSGALNACT2 in the occurrence and development of ovarian cancer and its correlation with immune infiltration and treatment of ovarian cancer has not been reported yet." (PMID 38082211, 2024). "In addition, the expression of CSGALNACT2 did not affect the prognosis of patients with ovarian cancer regardless of the increase or decrease of regulatory T cells." (PMID 38082211, 2024).
ovarian neoplasm (1 paper, 2024). A benign, borderline, or malignant neoplasm involving the ovary. "Clonogenic growth and enhanced cell migration are distinctive features of advanced tumors, suggesting that decreased CSGALNACT2 expression in ovarian neoplasms may potentially facilitate cancer progression." (PMID 38082211, 2024).
respiratory failure (1 paper, 2021). The significant impairment of gas exchange within the lungs resulting in hypoxia, hypercarbia, or both, to the extent that organ tissue perfusion is severely compromised. "Approximately 80% of Col2a1-Cre; Csgalnact1flox/—; Csgalnact2flox/— double cKO mice, which were deficient in both Csgalnact1 and Csgalnact2 in chondrocytes, immediately died after birth because of respiratory failure, and the remaining ∼20% of the double KO mice could start spontaneous respiration." (PMID 34901009, 2021). "Mice with double KO of Csgalnact1 and Csgalnact2 died during the postnatal stage due to respiratory failure." (PMID 34901009, 2021).
virus infection (1 paper, 2015). "However, to our knowledge, the role of CSGalNAcT2 in virus infection has not yet been reported." (PMID 25807054, 2015).
vitiligo (1 paper, 2025). Generalized well circumscribed patches of leukoderma that are generally distributed over symmetric body locations and is due to autoimmune destruction of melanocytes. "We identified seven proteins (HEPHL1, PRDX1, DEFA1, CSGALNACT2, HERC4, NDC80, and SPHK2) causally associated with vitiligo risk." (PMID 40856249, 2025).
tumor (2 papers, 2024 to 2025). "And, we observed that the expression of CSGALNACT2 decreased gradually as the tumor progressed, and the expression was significantly lower in the late stage than in the early." (PMID 38082211, 2024). "At the same time, the expression of CSGALNACT2 in tumor metastasis was significantly lower than that in the primary lesion." (PMID 38082211, 2024). "However, how CSGALNACT2 regulates immune infiltration and its role in anti-tumor immune response remains to be further studied." (PMID 38082211, 2024). "The oncogenic components, namely, ALDH1B1, ALDH1L2, CHSY1, CSGALNACT2, and GPX8, were progressively upregulated in more aggressive tumors, while the tumor suppressor hubs FBP1 and HPGD were downregulated as tumor aggressiveness increased." (PMID 40626022, 2025). "Increased CHSY1 and CSGALNACT2 expression remodels the extracellular matrix (ECM) through glycosaminoglycan biosynthesis, whereas downregulation of HPGD induces prostaglandin-driven inflammation, both of which are critical for tumor progression." (PMID 40626022, 2025).
CSGALNACT2 also shares sentences with these, for which no sentence is quoted: bladder cancer (1 paper); cancer (1); cervical squamous cell carcinoma (1); endocervical adenocarcinoma (1); glioma (1); infection (1); multiple myeloma (1); ovarian endometrioid adenocarcinoma (1); rectum adenocarcinoma (1); uterine corpus endometrial carcinoma (1).